ENSG00000279284 ( gene)
Gene: Gene on chromosome 6 (41,381,392 to 41,381,832, reverse strand). Ensembl gene ENSG00000279284.
Diseases named in the same sentence as ENSG00000279284 in open-access papers:
ENSG00000279284 is named in the same sentence as 181 diseases in open-access papers, as found by Europe PMC text mining. Sharing a sentence is not in itself a finding about the gene and the disease. The quoted sentences say what the papers report.
breast carcinoma (59 papers, 2003 to 2026). "Gene CENPF is a cell cycle-associated gene, and it has been identified as a marker of cell proliferation in breast cancers." (PMID 38741183, 2024). "This genome-wide association study, however, identified TYRP1 (rs41302073), a melanin synthesis regulatory gene, as a significant risk allele for breast cancer in their dataset that included African American and Barbadian women." (PMID 33659210, 2020). "Blm, the gene for Bloom syndrome, is a DNA repair gene which may play a role in breast cancer occurrence as its loss may contribute to somatic mutations and loss of heterozygosis, chromosomal instability, aneuploidy, and sensitivity to DNA damaging agents." (PMID 23967281, 2013). "Previous studies have confirmed that FOXO3a functions as a tumor suppressor gene in breast cancer, inhibiting VEGF-A/NRP1 signaling and breast cancer metastasis by driving miRNA signatures." (PMID 38566092, 2024). "Intriguingly, PDGFRL exhibits cell type-dependent roles, functioning as an oncogene in chondrocytes and as a tumor suppressor gene in breast cancer cells." (PMID 38848147, 2024). "Our previous study showed that it acts as a tumor suppressor gene in breast cancer through regulation of the MEK (mitogen-activated protein kinase kinase) signaling pathway via miR-665 targeting." (PMID 39664575, 2024). "Fisetin inhibits cell migration in mammary carcinoma by silencing the gene regulatory protein Nrf2 in the nuclear fraction, leading to reduced activity of MMP-9 and MMP-2." (PMID 38611849, 2024). "MiR-152, as a member of the miR-148/miR-152 family, is located on the chromosome 17, which functions as a tumor suppressor gene in many cancers including endometrial cancer, breast cancer and ovarian cancer." (PMID 38223603, 2023). "Coincidentally, miR-513a-5p has been shown to possess oncogenic potential in breast cancer and glioblastoma, while in contrast act as a tumor suppressor gene in osteosarcoma tissues." (PMID 36038573, 2022). "USP2 is a circadian rhythm-related gene that is involved in multiple biological processes, such as pressure overload-induced cardiac remodeling, breast cancer, hemophilia, and energy metabolism." (PMID 36172047, 2022). "Human breast cancer cells were transfected with p-14-3-3 sigma to overexpress the 14-3-3 sigma gene." (PMID 35890172, 2022). "ARID1A is a key neoplasm suppressor gene that cooperated with CEBPα inhibited UCA1 transcription in breast cancer." (PMID 33592583, 2021). "LINC00261 was confirmed by other studies to act as a tumor suppressor gene in prostate cancer, breast cancer, pancreatic cancer and many other types of cancers." (PMID 33928038, 2021). "In conclusions, Amot-p130 functions as a tumor suppressor gene in breast cancer, disrupting β-catenin stability by competing with Axin for binding to tankyrase." (PMID 30792381, 2019). "In recent years, PCDH17 was identified as a tumor suppressor gene for breast cancer, through promoter methylation." (PMID 31772653, 2019). "Recent studies also showed that estrogen up-regulate the expression of RERG a novel tumor suppressive gene which is highly expressed in ER + ve breast cancers." (PMID 29843638, 2018). "For example, in ER+ breast cancer, EglN2 is mainly regulated by estrogen and acts as a canonical estrogen inducible gene." (PMID 28036276, 2017). "Collectively, our results confirm that low levels of CSMD1 in breast cancer cells are associated with more aggressive cancer cell behavior, hence demonstrating the role of CSMD1 as tumor suppressor gene." (PMID 27764775, 2016). "Our results confirmed the role of PinX1 as a major tumor suppressor gene in breast cancer cell lines and provided information for further research on the molecular mechanisms of PinX1 in tumorigenesis." (PMID 24672800, 2014). "SERPINB5, also known as maspin (mammary serine protease inhibitor) is a class II tumor suppressor gene identified in patients with breast cancer." (PMID 25020046, 2014).
breast carcinoma (continued). "It was demonstrated, since its discovery as a metastasis suppressor gene that Nm23-H1 down-regulates LPA1 expression in breast cancers." (PMID 22200658, 2012). "The ZNF652 (17q21.32) locus codes for a DNA binding protein thought to act as a tumor suppressor gene in breast cancer that is also co-expressed with the androgen receptor in prostate cancer." (PMID 22829776, 2012). "In order to determine whether BNIP3L functions as a tumour suppressor gene in breast and/or ovarian cancer, we have analysed its expression in ovarian and breast cancer cell lines and screened all exons for mutations in a panel of primary ovarian and breast cancers." (PMID 12610513, 2003). "A recent study also found that LINC00486 may act as a tumor suppressor gene and its overexpression can inhibit the proliferation and promote the apoptosis of breast cancer tissues by suppressing miR-182–5p expression." (PMID 35399499, 2022). "Moreover, NEK6 also plays a role as a tumor-suppressor gene in different cancers, including thyroid cancer, gastric cancer, hepatic cell cancer, and breast cancer." (PMID 34834441, 2021). "On the other hand, the NRG1 gene is frequently silenced by methylation in breast cancers and NRG1 may be the principal tumor suppressor gene that leads to loss of the short arm of chromosome 8 in many breast and other epithelial cancers." (PMID 34044811, 2021). "Another potential candidate is CAV1 (caveolin-1), located at 7q31, which can act either as an oncogene (as described in bladder, thyroid, and esophageal cancers) or as a tumor suppressor gene (in ovarian, lung, and mammary tumors), depending on the tissue type or the microenvironmental influence." (PMID 34590593, 2021). "Claudin-6 (CLDN6), a tight junction protein, acts as a tumor suppressor gene in breast cancer." (PMID 31412908, 2019). "Low C/EBPα levels have been observed in breast cancer, and there is epigenetic silencing in acute myelogenous leukemia which together with our data suggest a general role of C/EBPα as a tumor suppressor gene." (PMID 30599048, 2019). "Recently, it was suggested that CDH11 acts as a tumor suppressor gene as demonstrated by its methylated and silenced status in malignant tissues such as in the nasopharyngeal, esophageal, gastric, hepatocellular carcinoma, colon, and breast carcinoma." (PMID 30691241, 2019). "Spalt like transcription factor 1 (SALL1) encodes a zinc finger transcriptional repressor, which has recently been identified as a tumor suppressor gene, whose expression was in positive correlation with CDH1 and associated with the survival of patients in breast cancer." (PMID 30233644, 2018). "Mapping of chromosome 3 structure in a single hTERT-repressed 21NT-#3fragment hybrid clone, revealed a 490kb region of deletion localised to 3p21.3 and encompassing the histone H3, lysine 36 (H3K36) trimethyltransferase enzyme SETD2; a putative tumour suppressor gene in breast cancer." (PMID 28977912, 2017). "Studies have shown that ERp29 may act as a tumor suppressor gene in breast cancer by regulating EMT process." (PMID 29108263, 2017). "Interestingly, KISS1 was first discovered as a metastasis suppressor gene and thought to play a role in suppression of metastasis of breast cancers and melanomas." (PMID 26056364, 2015). "In contrast to previous studies indicating Klotho as a putative tumor suppressor gene in human breast cancer, kidney cancer and lung cancer, our present study reveals the oncogenic function of Klotho in hepatocarcinogenesis, which is consistent with previous findings in epithelial ovarian cancer." (PMID 23516476, 2013). "Taken together, our data supported RARRES1 to be a tumor suppressor gene in breast cancer and its downregulation, by DNA methylation, CTCF binding, or by histone remodeling, might favor dissemination and survival of breast carcinoma." (PMID 22615834, 2012).
breast carcinoma (continued). "Our earlier results of NHERF1genetic alterations in human breast cancer prompted us to hypothesize that NHERF1 acts as a tumor suppressor gene in mammary gland." (PMID 18190691, 2008). "Taken together with the effects of ZFAS1 knockdown on mammary epithelial cell proliferation and differentiation, their results suggest ZFAS1 as a novel human tumor suppressor gene in breast cancer and that its dysregulation may be useful as a marker for breast cancer." (PMID 36406273, 2022). "Our findings suggest that ST5 potentially acts as a tumor suppressor gene in invasive breast cancer through regulating ERK/JNK signaling pathway and provide a novel insight for breast cancer treatment." (PMID 34395234, 2021). "Particularly melanoma, carcinoma and solid tumors have the most significant enrichment of these genes, including ABCC11 (melanoma drug resistance), SNRNP200 (retinitis pigmentosa), TRERF1 (breast cancer) and WTX (Wilms tumor gene on X chromosome, Wilms tumor)." (PMID 25523808, 2014). "Evidences suggest that GSN may act as a tumor suppressor gene, indeed, several studies showed a GSN down-regulation in human cancers including breast carcinoma." (PMID 30925779, 2019). "Interestingly, in some tumors with non-amplified MYCN (breast cancer, Wilms tumor), TSSC1 behaves as a tumor suppressor gene instead of an oncogene." (PMID 34830942, 2021).
gastric cancer (33 papers, 2014 to 2024). A primary or metastatic malignant neoplasm involving the stomach. "Previous study also reported that KLF4 was a proliferation- and metastasis-associated gene in gastric cancer." (PMID 28445396, 2017). "Thus, it was evident that miR-128, a tumor suppressor gene, is down-regulated in gastric cancer and is associated with metastatic disease." (PMID 28424413, 2017). "Accumulating evidence shows that miR-195-5p acts as a tumour suppressor gene in colorectal cancer, gastric cancer, lung adenocarcinoma, glioma, and CC." (PMID 37782756, 2023). "TSPAN5 has been shown to interact with ADAM10 and act as an oncogene in HCC and a tumor suppressor gene in gastric cancer." (PMID 37047447, 2023). "Consistently, we previously reported that miR-194 functioned as a tumor suppressor gene in gastric cancer." (PMID 36620589, 2022). "MiR-653-5p has been identified as an oncogene in PCa and gastric cancer, whereas acted as a tumor suppressor gene in cervical cancer, non-small cell lung cancer and melanoma." (PMID 34986849, 2022). "Vezatin, adherens junctions transmembrane protein (VEZT) has been identified as a tumor suppressor gene in gastric cancer." (PMID 35923577, 2022). "For example, as a tumor suppressor gene, miR-455-5p inhibited the proliferation and metastasis of gastric cancer cells by down-regulating the expression of Rab18." (PMID 34288799, 2021). "In recent years, research has indicated that miR-30c is actively involved in the regulation of malignant tumor signaling pathways and that it acts as a tumor suppressor gene in the majority of malignant tumors, such as renal cell carcinoma, colorectal cancer, gastric cancer, and breast cancer." (PMID 36180477, 2022). "A previous article testified that miR-6745 was low expressed in gastric cancer and miR-6745 overexpression reduced the growth of gastric cancer cells in vitro and in vivo, suggesting that miR-6745 might be a tumor suppressor gene in gastric cancer." (PMID 35935583, 2022). "Low expression of miR-149 in gastric cancer was detected by analyzing TCGA database and confirmed using qRT-PCR in 20 pairs of gastric cancer tissues and five gastric cancer cell lines, suggesting that miR-149 plays a role as a tumor suppressor gene in gastric cancer." (PMID 34957298, 2021). "miRNA‐646 has been reported to be down‐regulated in many human cancers and is involved in the development of many malignant tumours as a tumour suppressor gene, including colon cancer, pancreatic cancer, gastric cancer, lung cancer, osteosarcoma and clear cell kidney cancer." (PMID 32378344, 2020). "However, miR-24 was also found to be a tumor suppressor gene that inhibited gastric cancer progression by decreasing the gene expression of regenerating islet-derived family, member four." (PMID 26006243, 2015). "This indicates that the high methylation modification of PTCH1 as a tumor suppressor gene may be one of the main mechanisms of gastric cancer." (PMID 25013484, 2014). "Here we reported that ARHGAP15, a Rho GTPase activating protein, enhanced gastric cancer (GC) metastatic colonization, which was quite different from its reported role as a tumor suppressor gene in other cancers." (PMID 36802400, 2023). "In addition to the single hypoxia-related gene, the gene signature of several genes has been studied in several cancers, such as lung cancer and gastric cancers, which could achieve a more reliable prognostic value than the single one." (PMID 35789607, 2022). "Suppressor anaphase-promoting complex domain containing 2 (SAPCD2), also known as p42.3 or C9orf140, is a cell cycle-dependent gene which was first identified in the gastric cancer (GC) cell line, BGC823." (PMID 32055236, 2020). "This suggested that NAG-1 may function as a tumor-suppressor gene in gastric cancer carcinogenesis." (PMID 24348798, 2014).
gastric cancer (continued). "As a well-known negative regulator of cell cycle progression, CHFR was regarded as a tumor suppressor gene and hypermethylation in CHFR gene promoter were frequently observed in multiple cancer types, such as colorectal cancer and gastric cancer." (PMID 37024798, 2023). "As a tumor suppressor gene, lncRNA ZNF667-AS1 significantly hinders the propagation, metastasis, and angiogenesis of gastric cancer cells by promoting the expression of E-cadherin and inhibiting the expression of N-cadherin and VEGFA." (PMID 35813862, 2022). "The reduced expression of ATBF1 was consistent with that in other cancers, such as prostate cancer and gastric cancer, which suggested ATBF1 as a tumor suppression gene." (PMID 36476423, 2022). "PARK2 is frequently deleted in human tumors and is a tumor suppressor gene, although the precise role of PARK2 in gastric cancer requires more detailed investigation." (PMID 28603669, 2017). "Previous studies demonstrated that miR-760 may act as a tumor suppressor gene in non-small cell lung cancer (NSCLC), colorectal cancer and gastric cancer." (PMID 36153332, 2022).
colorectal cancer (31 papers, 2008 to 2026). A primary or metastatic malignant neoplasm that affects the colon or rectum. "Axin2, as a target gene of the Wnt signaling pathway, was previously categorized as a tumor suppressor gene in a small fraction of colorectal cancers harboring APC gene mutations." (PMID 35875099, 2022). "Myosin IIA is considered a tumor-suppressing gene, but recent studies have reported that high protein expression is associated with poor overall survival in colorectal cancer, suggesting that myosin IIA may have an oncogenic role." (PMID 36139553, 2022). "NDST4 was previously identified as a putative tumor-suppressor gene in human colorectal cancer and its genetic loss might be related to the colorectal cancer progression." (PMID 29297280, 2017). "In addition, a previous study on colorectal cancer showed that methylation of another DNA repair gene, MGMT, is also linked to MSI." (PMID 23414134, 2013). "miR-342 has also been demonstrated to act as a tumor suppressor gene that inhibits the growth of colorectal carcinoma by regulating aberrant DNA hypermethylation." (PMID 36310619, 2022). "miR‐138‐5p was weak‐expressed in some kinds of cancers: It acted as a tumor suppressor gene in colorectal cancer to imped cell proliferation, and aerobic glycolysis served as a competing endogenous RNA." (PMID 34586647, 2021). "S100A4 is a well-known metastasis-inducing gene in colorectal cancer and S100A4 inhibition for therapeutic intervention is suggested." (PMID 31581665, 2019). "The heart and neural crest derivatives expressed 1 (HAND1), belonging to the basic helix-loop-helix family of transcription factors, is showed to be a tumor suppressor gene in colorectal cancer." (PMID 31565069, 2019). "On one hand IGFBP7 has recently been described as a tumour suppressor gene in colorectal cancer and was shown to induce senescence in cells harbouring oncogenic BRAF, whereas on the other hand IGFBP7 was shown to have oncogenic properties in gliomas." (PMID 20579385, 2010). "Previous research shown that miR-384 may act as a tumor suppressor gene in colorectal cancer 53, oral squamous 54 and prostate cancer." (PMID 39132166, 2024). "Integral membrane protein 2C (ITM2C), a member of the ITM protein family, is considered a tumor suppressor gene in colorectal cancer and may inhibit tumor cell growth and division." (PMID 38531846, 2024). "Sirt1 has also been reported to be an autophagy-related gene in colorectal cancer." (PMID 38214831, 2024). "miR-338-3p has been found to function as a tumor suppressor gene in colorectal cancer, and can be used as a downstream target gene for a variety of lncRNAs to function as oncogenes to regulate biological characteristics of colorectal cancer cells, including LINC0052510." (PMID 35156520, 2022). "Finally, miR-637 has been reported to be a tumor suppressor gene in diverse human cancers, such as gastric, ovarian and colorectal cancers." (PMID 32211330, 2020). "This is consistent with the role of CDX2 as a tumor-suppressor gene in colorectal cancer." (PMID 25847407, 2015). "Moreover, ENO2 is a glycolysis-related gene that has been described to play an important role in tumorogenesis of colorectal cancers." (PMID 18694510, 2008). "Therefore, we hypothesize that Egr-1 regulate the expression of NGX6 gene in colorectal cancer as a tumor suppressor gene." (PMID 25029911, 2014). "In colorectal cancer, FHL1 has been reported to be a tumor suppressor gene by negatively regulating the Wnt/β-catenin signaling pathway." (PMID 40831931, 2025). "It serves as a candidate colorectal tumor suppressor gene and suppresses cell proliferation and WNT/β-catenin pathway in colorectal cancer cells." (PMID 35524260, 2022).
colorectal cancer (continued). "The metastasis-inducing gene MACC1 is a newly identified gene and its expression is a prognostic indicator for colorectal cancer metastasis." (PMID 22838389, 2012).